SPTAN1 (spectrin alpha, non-erythrocytic 1)
Diseases named in the same sentence as SPTAN1 in open-access papers (continued):
Sharing a sentence is not in itself a finding about the gene and the disease.
prostate carcinoma (3 papers, 2018 to 2022). A carcinoma that arises from epithelial cells of the prostate gland. "The anticancer drug bicalutamide, clinically used in prostate cancer patients, has been shown to enhance SPTAN1-mediated apoptosis by calpain or caspase 3 leading to cell shrinkage and membrane blebbing." (PMID 31186638, 2019). "In prostate cancer cells, SPTAN1 cleaved by calpain induced apoptosis upon treatment with the anticancer drug bicalutamide." (PMID 31186638, 2019). "However, reduced SPTAN1 expression was found in a lung metastasis of a prostate cancer patient." (PMID 31186638, 2019). "Until now, no data regarding the expression level of SPTAN1 in prostate carcinomas are available." (PMID 31186638, 2019).
Alzheimer disease (2 papers, 2023 to 2025). A progressive, neurodegenerative disease characterized by loss of function and death of nerve cells in several areas of the brain leading to loss of cognitive function such as memory and language. "Therefore, we believe that SPTAN1 is also a key potential molecule associated with Alzheimer’s disease." (PMID 36915078, 2023).
autism (2 papers, 2023 to 2025). Persistent deficits in social interaction and communication and interaction as well as a markedly restricted repertoire of activity and interest as well as repetitive patterns of behavior. "Spectrin members of the cytoskeletal scaffold proteins α2 spectrin (SPTAN1) and β3 spectrin (SPTBN2) were significantly decreased in children with autism." (PMID 40779003, 2025).
bladder cancer (2 papers, 2023 to 2024). "The most frequently mutated genes in ordinary bladder cancer are TP53x, KMT2A, SPTAN1, ERBB2, CREBBP, FAT1, ATM, and KMT2C." (PMID 36779496, 2023). "Additionally, the most frequently mutated genes in ordinary bladder cancer are KMT2C, ATM, FAT1, CREBBP, ERBB2, SPTAN1, and KMT2A." (PMID 39399176, 2024).
hepatocellular carcinoma (2 papers, 2023 to 2025). A malignant tumor that arises from hepatocytes. "To establish the pathological relevance of SPTAN1, NUMB, MARK, WW45, and Hippo/MST1/2/YAP signals in patients with hepatocellular carcinoma (HCC), we examined 60 pairs of liver-derived tumorous and adjacent nontumorous tissues." (PMID 37843276, 2023). "This study investigates the lactylation (kla) modification of SPTAN1 (SPTAN1-kla) and its mechanistic contributions to hepatitis B virus (HBV)-related hepatocellular carcinoma (HCC)." (PMID 41243220, 2025).
liver cancer (2 papers, 2023). An epithelial or non-epithelial malignant neoplasm that arises from the liver. "Inactivation of 1 allele of Yap was sufficient to rescue hepatomegaly and liver cancer development in Sptan1 Ww45 double-KO mice." (PMID 37843276, 2023). "Moreover, NUMB3/4, with their truncated PTB domains that render them unable to interact with SPTAN1 and activate MST1/2, were preferentially upregulated in liver cancer, along with a reduction of phosphorylated SPTAN1 (p-SPTAN1), which correlated with YAP activation." (PMID 37843276, 2023). "Interestingly, NUMB isoforms 3 and 4, which have a truncated phosphotyrosine-binding (PTB) domain and are thus unable to interact with phosphorylated SPTAN1 and activate MST1/2, were selectively upregulated in liver cancer, which correlated with YAP activation." (PMID 37843276, 2023).
melanoma (2 papers, 2019 to 2025). A malignant, usually aggressive tumor composed of atypical, neoplastic melanocytes. "Basal as well as squamous cell carcinomas and malignant melanomas display increasing invasion and metastatic capacities, probably reflected by the different patterns of SPTAN1 expression." (PMID 31186638, 2019). "Therefore, the expression of SPTAN1 in melanomas must be clarified by further investigation." (PMID 31186638, 2019). "In melanomas, however, some cells were strongly stained, while others were completely negative for SPTAN1." (PMID 31186638, 2019).
oral cancer (2 papers, 2017 to 2025). "Additionally, down-regulation of cytoskeletal proteins, including SH3GLB2 (endophilin-B2), spectrin (SPTAN1), and annexin (ANXA2) in T2D individuals mirrors the pattern seen in oral cancers and precancerous lesions." (PMID 39794871, 2025).
cognitive deficits (1 paper, 2023). "SPTAN1 is downregulated in the hippocampus of patients with medial temporal lobe epilepsy(MTLE), which is usually involved in drug-resistant seizures and cognitive deficits." (PMID 36915078, 2023).
colorectal tumours (1 paper, 2021). "We first compile survival data from our previously characterised CRC cohort and show that patient survival is linked to SPTAN1 protein levels in colorectal tumours." (PMID 34298848, 2021). "We show here that increased levels of SPTAN1 are associated with longer overall survival times in patients with colorectal tumours." (PMID 34298848, 2021). "We then analyse gene expression data from The Cancer Genome Atlas (TCGA) to corroborate our findings at the transcriptional level, and to further delineate the association of SPTAN1 mRNA levels with epithelial cohesion, colorectal tumour invasiveness, and patient responses to FOLFOX chemotherapy." (PMID 34298848, 2021). "This study provides evidence of a link between patient outcomes and SPTAN1 expression levels in colorectal tumours." (PMID 34298848, 2021). "We next looked for features of tumour biology that might explain why patients with colorectal tumours expressing high levels of SPTAN1 have favourable survival outcomes." (PMID 34298848, 2021).
deafness (1 paper, 2022). An inherited or acquired condition characterized by the complete loss of the ability to hear from one or both ears. "Interestingly, mice with HC-specific Sptan1 knockout exhibited rapid deafness, abnormal formation of stereocilia and cuticular plates, and loss of HCs from middle and apical turns of the cochlea during early postnatal stages." (PMID 34708331, 2022). "Sptan1-CKO mice presented with rapid OHC loss and early-onset deafness." (PMID 34708331, 2022).
dementia (1 paper, 2017). Loss of intellectual abilities interfering with an individual's social and occupational functions. "These dementia-specific HCit-containing proteins include brain acid soluble protein 1 (BASP1), spectrin alpha chain 1 (SPTAN1), and glial fibrillary acidic protein (GFAP)." (PMID 28865468, 2017).
dyslexia (1 paper, 2023). A learning disorder characterized by an impairment in processing written words. "Patients with SPTAN1 mutations have also been found to present with peripheral neuropathy, severe dyslexia, and executive function difficulties." (PMID 36915078, 2023).
gastric cancer (1 paper, 2019). A primary or metastatic malignant neoplasm involving the stomach. "In the first study, published in 2002, Lee and coworkers identified SPTAN1 as a differentially expressed gene in gastric cancer using cDNA microarrays." (PMID 31186638, 2019). "Until now, only two studies have described SPTAN1 expression in gastric cancer." (PMID 31186638, 2019).
Hypertension (1 paper, 2022). The presence of chronic increased pressure in the systemic arterial system. "Most significantly, the low-renin SNP rs12336898 in the SPTAN1 gene, closely related to vascular wall remodeling, was associated with the development of hypertension (p-value = 1.3 × 10−6)." (PMID 35448080, 2022). "In summary, we revealed an association between rs12336898 in SPTAN1 and hypertension in the low-renin group." (PMID 35448080, 2022). "Moreover, our results indicate that polymorphisms in the downstream region of the SPTAN1 gene contribute to the incidence of hypertension." (PMID 35448080, 2022). "This study identifies a relationship between rs12336898 in the SPTAN1 gene and hypertension in low-renin subjects." (PMID 35448080, 2022). "Pathogenesis of the SPTAN1 gene and hypertension via the RAS support these findings." (PMID 35448080, 2022).
infantile epilepsy (1 paper, 2025). "At the protein level, western blots validated expression changes in CBS (mental retardation), NEAS/SPTAN1 (associated with infantile epilepsy), FBLN1 (cardiac morphogenesis), FXR1 (muscle development), and SHANK2 (neuronal differentiation in the retina)." (PMID 39508990, 2025).
leukemia (1 paper, 2019). A malignant (clonal) hematologic disorder, involving hematopoietic stem cells and characterized by the presence of primitive or atypical myeloid or lymphoid cells in the bone marrow and the blood. "In leukemia cell lines, enhanced expression of heterodimeric SPTAN1/SPTBN1 was shown to be induced by dimethyl sulfoxide (DMSO) treatment followed by local rearrangement of this protein complex." (PMID 31186638, 2019). "Interestingly, SPTAN1 was mapped near the translocation breakpoint region on chromosome 9 in the Abelson murine leukemia (ABL) protooncogene which is involved in the formation of the Philadelphia chromosome in leukemia." (PMID 31186638, 2019).
Lynch syndrome (1 paper, 2014). An autosomal dominant hereditary neoplastic syndrome characterized by the development of colorectal carcinoma and a high risk of developing endometrial carcinoma, gastric carcinoma, ovarian carcinoma, renal pelvis carcinoma, and small intestinal carcinoma.
Obesity (1 paper, 2022). Accumulation of substantial excess body fat. "ALPK3, HLF, FXN, and SPTAN1 are the only genes that have never been linked to obesity." (PMID 35677823, 2022).
pneumonia (1 paper, 2022). An acute, acute and chronic, or chronic inflammation focally or diffusely affecting the lung parenchyma, caused by an infection in one or both of the lungs (by bacteria, viruses, fungi, or mycoplasma.). "The multi-omic context of SPTAN1 proved to be interesting by being connected to pneumonia and T2D as comorbidity and tibial artery as tissue." (PMID 35903362, 2022).
renal carcinoma (1 paper, 2023). A carcinoma arising from the epithelium of the renal parenchyma or the renal pelvis. "On the contrary, 3 are linked with a favorable prognosis for renal cancer (SPTAN1, SPTBN1, CAVIN2)." (PMID 37775701, 2023). "SPTAN1 and FBLN5 are favorable prognostic markers in renal cancer but unfavorable in OC (considering a p < 0.05)." (PMID 37775701, 2023).
sarcoma (1 paper, 2019). A usually aggressive malignant neoplasm of the soft tissue or bone. "The expression of SPTAN1, identified by gene expression profiling, was higher in more aggressive types of desmoid-type fibromatosis and malignant mesenchymal tumors compared to benign mesenchymal tumors." (PMID 31186638, 2019). "This might be due to a different metastatic pattern of sarcomas compared to carcinomas, which metastasize rather to the lung and liver than to lymph nodes, and missing information on the role of SPTAN1 in this regard." (PMID 31186638, 2019).
squamous carcinoma (1 paper, 2019). "In noninvasive squamous carcinoma cells, SPTAN1 was detected in podosomes, whereas it was absent in invasive invadopodia, suggesting a tumor preventing role." (PMID 31186638, 2019).
tumor (17 papers, 2007 to 2026). "We previously demonstrated a close correlation between MLH1 deficiency, low SPTAN1 expression, tumor progression and the degree of metastasis." (PMID 38891846, 2024). "We find that, after taking into account patient age and UICC tumour stage, elevated intratumoural SPTAN1 protein and mRNA levels associate with favourable survival outcomes." (PMID 34298848, 2021). "In bladder cancer, SPTAN1 was identified in recurrence-associated gene signatures and suggested as a predictor of disease recurrence at an early tumor stage." (PMID 31186638, 2019). "Taken together, we demonstrate that MLH1 deficiency, low SPTAN1 expression, and tumor progression and metastasis are in close relation." (PMID 30856214, 2019). "We conclude that SPTAN1 is a candidate molecule explaining the tumor progression and metastasis of MLH1-deficient CRCs." (PMID 30856214, 2019). "A role for SPTAN1 as a tumor suppressor is indicated by the decline of SPTAN1 in tumor-prone FA patients and in MMR-deficient CRCs." (PMID 31186638, 2019). "Overall, we find that upregulation of actin cytoskeletal genes in bulk expression data is associated with increasing tumour stage and poor survival outcomes, whereas increased expression of SPTAN1 and other genes involved in focal adhesion predicts better overall survival." (PMID 34298848, 2021). "Specifically, enhanced cytoplasmic SPTAN1 is associated with neoplasia and progression." (PMID 31186638, 2019). "A possible explanation for the divergent SPTAN1 levels within the MLH1-deficient tumor group could be that the influence of MLH1 on SPTAN1 expression is indirect and occurs at the mRNA level." (PMID 30856214, 2019). "SPTAN1 expression might decrease along with the loss of epithelial polarity accompanying tumor development and progression, which would actually mean that lower SPTAN1 expression favors the metastatic ability of tumor cells." (PMID 30856214, 2019). "Moreover, enhanced SPTAN1 was linked to tumor progression and malignancy in ovarian cancer and described to be involved in the carcinogenesis of sporadic CRC." (PMID 24456667, 2014). "Therapeutic targeting of SPTAN1-kla using specific inhibitory peptides significantly attenuates HCC tumor growth in preclinical models." (PMID 41243220, 2025). "We found that, although the protein levels of SPTAN1 were comparable in the T and N samples, p-Tyr SPTAN1 was remarkably reduced in a high fraction of tumor samples." (PMID 37843276, 2023). "Conversely, the utility of SPTAN1 in determining tumour aggressiveness and predicting patient outcomes is less clear-cut." (PMID 34298848, 2021). "The effects of SPTAN1 expression on tumour biology therefore only provide a partial explanation for the favourable survival outcomes of patients with SPTAN1-high CRCs." (PMID 34298848, 2021). "This is perhaps unsurprising, given that SPTAN1 can assume the role of both tumour promoter and suppressor, as reflected in the results of our GSEA analysis." (PMID 34298848, 2021). "These latter findings suggest that differential SPTAN1 transcript levels in our bulk expression data reflect tumour cell-intrinsic fluctuations in SPTAN1 gene expression, rather than variations in the degree of immune or stromal infiltration of the TME." (PMID 34298848, 2021). "Beyond its role in tumour biology, we were able to identify a link between SPTAN1 gene expression and patient responses to FOLFOX chemotherapy." (PMID 34298848, 2021). "Our pathway analysis reinforces the notion that, depending on the cellular context, SPTAN1 can be both a tumour promoter and a tumour suppressor." (PMID 34298848, 2021). "Next, we included the obtained enrichment scores in our proportional hazards model, along with patient age, tumour stage, and SPTAN1 mRNA levels." (PMID 34298848, 2021). "We therefore suggest that increased SPTAN1 expression sensitises cancers to FOLFOX chemotherapy, thereby contributing to the superior survival outcomes observed in patients with SPTAN1-high tumours." (PMID 34298848, 2021).
tumor (continued). "Overall, our study underscores the importance of cytoskeletal proteins in shaping tumour biology and treatment responses and nominates SPTAN1 as a biomarker to improve patient stratification and refine therapeutic decisions in CRC." (PMID 34298848, 2021). "The clear survival advantage in the SPTAN1-high group was maintained after adjusting for patient age and tumour stage in a proportional hazards model (hazard ratio in the SPTAN1-high group, 0.49; 95% confidence interval, 0.30 to 0.81; p = 0.005)." (PMID 34298848, 2021). "SPTAN1 protein levels in each of the 182 tumours were analysed by immunohistochemistry as part of our previous study." (PMID 34298848, 2021). "Conversely, subgroup analysis of UICC stage III and IV tumours showed improved overall survival in the SPTAN1-high group compared with the SPTAN1-low group (hazard ratio in the SPTAN1-high group, 0.43; 95% confidence interval, 0.21 to 0.90; p = 0.025)." (PMID 34298848, 2021). "It is conceivable that SPTAN1 bypasses degradation and thus enables tumor cells to evade apoptosis due to overexpression and altered localization of SPTAN1 or altered binding properties to interacting proteins." (PMID 31186638, 2019). "Due to the wide range of SPTAN1's actions, it can potentially influence several or even every step from tumor development to progression and metastasis." (PMID 31186638, 2019). "On the other hand, nuclear SPTAN1 can have tumor suppressing effects by enabling DNA repair through interaction with DNA repair proteins." (PMID 31186638, 2019). "Looking at soft tissue tumors (SFTs), increasing SPTAN1 level and more aggressive tumor behavior were also described." (PMID 31186638, 2019). "We found evidence for a close correlation between MLH1 and SPTAN1 expression levels, and between the amount of SPTAN1 and tumor progression and metastasis." (PMID 30856214, 2019). "We detected significantly increased SPTAN1 levels in MLH1-proficient tumor tissue compared with normal mucosa (p<0.0001)." (PMID 30856214, 2019). "Most importantly and promising for clinical practice, SPTAN1 has the potential to be used as a tumor marker for progression as well as a marker for therapy decisions." (PMID 31186638, 2019). "As described in detail above, a change of SPTAN1 expression level has been found in various tumor entities." (PMID 31186638, 2019). "SPTAN1 has been described in cancer and therapy response and proposed as a potential marker protein for neoplasia, tumor aggressiveness, and therapeutic efficiency." (PMID 31186638, 2019). "Increased SPTAN1 expression has been described in various tumor entities including CRC, and appears to be related to tumor progression and invasion." (PMID 30856214, 2019). "Comparing the SPTAN1 expression of all tumor tissues, we found a trend of reduced SPTAN1 expression in MLH1-deficient vs. MLH1-proficient tumors (p = 0.271)." (PMID 30856214, 2019). "On one hand, the existing data suggest that overexpression of SPTAN1 in tumor cells reflects neoplastic and tumor promoting activity." (PMID 31186638, 2019). "In the fresh biopsy tissue from the CRC patient, SPTAN1 was well detectable in the normal tissue (lane 2) while the corresponding tumor showed reduced expression (lane 1)." (PMID 24456667, 2014). "Using different MLH1 deficient and proficient cell lines, paraffin embedded as well as fresh tumor tissue, we show for the first time that MLH1 deficiency decreases SPTAN1 expression with the functional consequence of impaired cellular migration." (PMID 24456667, 2014). "Deregulation of spectrins, especially of SPTAN1 seriously affects cellular behavior and promotes tumor progression." (PMID 24456667, 2014). "Since SPTAN1 is an important cytoskeletal protein that plays a major role in cell polarity, a direct correlation between increased IL-8 expression and reduced SPTAN1 expression could be assumed in our tumor model." (PMID 38891846, 2024).